INS (insulin)
Diseases named in the same sentence as INS in open-access papers (continued):
Sharing a sentence is not in itself a finding about the gene and the disease.
metabolic syndrome (continued). "(ii) The involvement of the glucose-insulin axis may also explain the association of the metabolic syndrome with an increased risk for several cancers." (PMID 22029671, 2011). "Nevertheless, many of these newer agents including tipranavir are associated with dyslipidemia and may therefore indirectly contribute to impaired insulin signaling." (PMID 21966466, 2011). "A recent study of non-diabetic Caucasians reported the association of promoter variant, +183A > G (rs5744292), which is in complete LD with rs1946519 and rs3882891, with increased levels of serum IL-18, increased risk of metabolic syndrome and impaired insulin sensitivity." (PMID 20227263, 2011). "Along with triglycerides, there was increase in other biochemical parameters associated with the metabolic syndrome such as uric acid and plasma insulin levels although blood cholesterol and glycated haemoglobin were not significantly affected in this rat model." (PMID 21794123, 2011). "Interestingly, a locus on murine chromosome 4 has been associated with markers of the Metabolic Syndrome, including body weight, insulin, leptin and triglyceride." (PMID 22078008, 2011). "In the present study we evaluated whether oral administration of raw garlic homogenate improves insulin sensitivity and associated metabolic syndrome in fructose fed rats." (PMID 21794123, 2011). "The reviewed studies indicate that these risk factors typical of metabolic syndrome are linked with the disturbed hepatic ER function affecting the fate of lipids, proteins, glucose and insulin.The studies also show that gene-activating therapy can eliminate abnormalities in the syndrome." (PMID 21568932, 2011). "Therefore the insulin deficiency related to metabolic syndrome in pancreas is due to both the cellular damage and the impaired efficiency in the synthesis of insulin." (PMID 20480025, 2010). "Furthermore, we can also find evidence which shows that physical activity is associated with improvement in elements of the metabolic syndrome, such as lower fasting insulin and greater insulin sensitivity in children and reduction in LDL-c and diastolic BP." (PMID 20236509, 2010). "However, these subjects had an associated metabolic syndrome (elevated insulin and inflammatory markers) and were obese." (PMID 19804639, 2009). "We hypothesized that the PRO weight loss diet would result in greater fat mass loss and more favorable changes in post-prandial INS response and features of dyslipidemia compared to an isocaloric CHO diet." (PMID 18990242, 2008). "However it was recently shown that metabolic syndrome components impacted selectively on IMT at the femoral site: insulin and triglyceride concentrations were strongly associated with femoral IMT but not with carotid IMT." (PMID 17958881, 2007). "As the rats age and become diabetic, GLUT5 abundance and activity is compromised, causing an even more marked insulin resistance over lean rats, implying a possible role of GLUT5 receptors in the pathology of metabolic syndrome associated with fructose feeding and insulin resistance." (PMID 15723702, 2005). "Additionally, MNPs bioaccumulate and act as "Trojan Horses," transporting toxicants that dysregulate insulin signaling, elevate corticosterone, and promote metabolic disorders, including obesity, insulin resistance, and dyslipidemia - all established cardiovascular risk factors." (PMID 40642717, 2025). "A systematic review showed that following the DASH dietary pattern with a 20% reduction in cardiovascular disease (CVD) risk, and the risk of coronary heart disease was reduced by 21%, which may be associated with improvement of metabolic syndrome and insulin sensitivity, reduction of inflammation." (PMID 41229546, 2025). "Moreover, FBG, fasting C-peptide, fasting insulin, and TC also showed a progressive upward trend, indicating that FFAs may be closely linked to various factors associated with metabolic syndrome." (PMID 40593032, 2025).
metabolic syndrome (continued). "However, no previous studies have assessed associations with cardiometabolic risk markers like insulin sensitivity and paediatric metabolic syndrome score during childhood, which may provide further insights on the early origins of cardiometabolic diseases." (PMID 38279175, 2024). "Insulin deficiency or resistance may be responsible for dyslipidemia, because insulin has an inhibitory action on 3-hydroxy-3-methylglutaryl coenzyme A (HMG-COA) reductase, a key enzyme which is responsible for the metabolism of LDL-c particles rich in cholesterol." (PMID 35237941, 2023). "Additionally, liver inflammation via acetaldehyde production may be observed, inducing de novo lipogenesis, and promoting hepatic insulin resistance, dyslipidemia, and hepatic steatosis, similar to the effects caused by added fructose." (PMID 38008803, 2023). "Active or passive physical inactivity and positive energy balance duringquarantine could induce many health consequences, including higher total body andcentral fat, reduced insulin sensitivity, and inflammatory status, which are themain risk factors for metabolic syndrome (MetS)." (PMID 39076704, 2023). "Interestingly, we found that metal disturbances are tightly inter-related to the typical hallmarks behind childhood obesity and comorbidities, namely OS, inflammation, impaired insulin metabolism, and dyslipidemia, and in turn can be modulated by different risk factors." (PMID 37672200, 2023). "However, it is conceivable that long-term variability of other DM-related risk factors (insulin levels, blood pressure, dyslipidemia, heart rate, body weight, and serum uric acid) may be involved in the development of AAA." (PMID 37034348, 2023). "Additionally, a large population-based study of 1,351 workers found that rotating shift workers exhibited higher fasting insulin values compared to their dayshift counterparts, which contributed to a 1.5-fold greater risk of metabolic syndrome when combined with other observed risk factors." (PMID 35615722, 2022). "Visceral fat is characterized by higher lipolytic activity than subcutaneous fat; the consequent excessive release of free fatty acids (FFA) could trigger hepatic insulin resistance, modifications of systemic lipid metabolism, and consequent overt dyslipidemia, leading to increased CVD risk." (PMID 36430774, 2022). "Some studies have come up with a logic that vitamin D affects the β-cell function and insulin sensitivity which may be a potential pathogenic mechanism for the development of dyslipidemia in vitamin D deficiency, as the dyslipidemia is closely related to the insulin sensitivity." (PMID 34017921, 2021). "Consistent with other markers of metabolic syndrome, a low-carbohydrate diet consistently decreases blood pressure in individuals with hypertension, which is likely mediated in part by lower circulating insulin levels and the associated natriuretic/diuretic effect described previously." (PMID 34684300, 2021). "Therefore, there may be a direct functional link between insulin function and amylase production, thus creating a causal link between starch digestion, glucose homeostasis and metabolic syndrome." (PMID 34444230, 2021). "In addition, oxidative stress, secondary to dyslipidemia, may ultimately cause decreased insulin gene expression and insulin secretion impairment." (PMID 34229731, 2021). "Moreover, it is currently thought that the underlying cause of metabolic syndrome originates from dysregulation in insulin and glucose handling in response to adiposity, and therefore, are often the first risk factors to present clinically (followed by dyslipidemia and hypertension)." (PMID 32218114, 2020). "The loss of muscle and the accumulation of intramuscular fat might be associated with metabolic syndrome via a complex interplay of factors including oxidative stress, proinflammatory cytokines, insulin resistance, hormonal changes, and mitochondrial dysfunction." (PMID 32859211, 2020).
metabolic syndrome (continued). "To determine whether dyslipidemia could contribute to preventing leptin for glucose-lowering effects in insulin-deficient RIP-CreΔLEPR mice, we first measured circulating FFAs, ketone bodies, glycerol, and TG in RIP-CreΔLEPR-LEP at 10 days after the beginning of leptin administration." (PMID 33071988, 2020). "PLT may ameliorate metabolic syndrome and improve insulin sensitivity caused by diet." (PMID 33302947, 2020). "Dopaminergic agonists such as bromocriptine suppress insulin and leptin release by reducing peak amplitude of their rhythmic release, and have been associated with improved metabolic function in obese subjects with metabolic syndrome, and subjects suffering from T2D." (PMID 30364286, 2018). "Currently, the main treatments for metabolic syndrome are weight loss and physical activity; however, there is also evidence that pharmacotherapy (insulin sensitizers, statins, angiotensin-converting enzyme inhibitors) and, more recently, nutritional strategies could be beneficial." (PMID 30400297, 2018). "Although glucose tolerance differed between the ND-fed mice and those on the modified diets, only the HFD-fed mice were clearly insulin-resistant, suggesting that increased fasting blood glucose levels, dyslipidemia, and glucose intolerance may be caused by increased endotoxin levels." (PMID 29899272, 2018). "Additionally, previous research shows that narcolepsy patients may be more insulin sensitive with a lower rate of lipolysis, which suggests an increased risk for narcolepsy patients in developing metabolic syndrome." (PMID 30574118, 2018). "In addition, low-dose ABA does not increase insulin release and this may prove advantageous in diabetic, prediabetic, and metabolic syndrome subjects, who are deficient in and/or resistant to insulin." (PMID 28660193, 2017). "Numerous genes are also linked to an increased susceptibility to dyslipidemia, particularly peroxisome proliferator-activated receptor γ (PPARγ), a nuclear receptor that regulates adipocyte differentiation, lipid storage, fat-specific gene expression and insulin action." (PMID 27894098, 2017). "Impaired insulin sensitivity is considered an important risk factor for atherosclerotic disease, and a key determinant of cardiovascular risk factors, including visceral obesity, atherogenic dyslipidemia, and hypertension, clustering within the metabolic syndrome." (PMID 28426788, 2017). "Unfortunately, the insulin resistant reallocation of resources persists in chronic stress conditions such as food insecurity and may be aggravated by stress eating, accentuating risk for dyslipidemia." (PMID 26866948, 2016). "In addition to muscle atrophy, inactivity and ageing are commonly associated with increased adiposity, together leading to metabolic dysfunctions such as dyslipidemia, decreased insulin sensitivity, hyperglycemia and an increased risk of developing diabetes mellitus (i.e., T2D)." (PMID 26203859, 2015). "Animal studies have demonstrated that exposure to smoking or nicotine during the prenatal and neonatal periods could impair insulin sensitivity, decrease beta cell function, impair glucose tolerance, and increase the susceptibility to metabolic syndrome in the offspring." (PMID 26599278, 2015). "In fact, metabolic syndrome encompassing these conditions has also been shown to be associated with retinopathy where many overweight type 1 diabetic patients are difficult to treat and require a relatively high dose of insulin to achieve adequate glycemic control." (PMID 24696683, 2014). "Thus, DHA may help in prevention of the metabolic syndrome by improving intestinal integrity, improving insulin sensitivity, and decreasing LPS- or adipose-associated systemic inflammation." (PMID 23966110, 2013).
metabolic syndrome (continued). "The association of fasting insulin with incident outcomes attenuated with adjustment for potential confounders (model 2), with little further attenuation upon additional adjustment for other components of metabolic syndrome and LDL-c (model 3) or for fasting glucose and HbA1c (model 4)." (PMID 17760500, 2007). "Patients with the metabolic syndrome typically require a“cocktail of drugs” to treat the individual components of thedisorder and its associated atherosclerotic complications (e.g.,oral hypoglycaemic agents, insulin, statins, fibrates,antihypertensives, aspirin, etc.)." (PMID 17389771, 2007). "This study aimed to investigate real-world evidence for the effects of semaglutide dose escalation on HbA1c, body weight, dyslipidemia, and insulin dose reduction in patients with T2DM in the Cukurova region of Türkiye." (PMID 42278967, 2026). "In the dexamethasone protocol, LASSBio-1986 improved insulin sensitivity, attenuated dyslipidemia, reduced TBARS levels and restored GSH in metabolically active tissues." (PMID 41596477, 2026). "The search strategy incorporated a combination of the following keywords: Microgravity, Sedentary lifestyle, Insulin resistance, Ectopic fat, Metabolic syndrome, Steatotic Liver, and Pancreatic Diseases." (PMID 42109715, 2026). "Our findings demonstrate that EPP intervention significantly suppressed fasting blood glucose (FBG) levels, attenuated dyslipidemia, and enhanced systemic insulin sensitivity." (PMID 42282445, 2026). "Further, VAT is known to secrete free fatty acids into the portal vein and circulation, contributing to hepatic steatosis, hepatic and muscle insulin resistance, vascular dysfunction and dyslipidemia." (PMID 41251158, 2026). "Clinical studies indicate that polyphenol-rich diets, such as the Mediterranean diet, improve metabolic syndrome parameters by lowering inflammatory markers, enhancing lipid profiles, and improving insulin sensitivity." (PMID 42131482, 2026). "Supplementation with GCE reduced body weight gain and adipose tissue accumulation, improved dyslipidemia and insulin sensitivity, and enhanced hepatic antioxidant capacity in high-fat model mice." (PMID 41754155, 2026). "Old age keywords showed substantially higher association with OFS keywords (e.g., φ = 0.06 for elderl* and hip fracture, p < 0.05) than with metabolic syndrome terms (elderl* and insulin resistance, p > 0.05)." (PMID 42074906, 2026). "FBA supplementation exhibited superior effects in attenuating body weight gain, visceral adiposity, dyslipidemia, and hepatic steatosis while improving insulin sensitivity." (PMID 41729130, 2026). "Another common focus of RCTs is the lipid profile in patients with T2DM, owing to the strong correlation between dyslipidemia and key drivers of disease progression, such as oxidative stress and impaired insulin sensitivity." (PMID 41439937, 2025). "Among all examined parameters, insulin demonstrated the strongest effect, underscoring its key role in the development of overweight and metabolic syndrome." (PMID 41002975, 2025). "First, as an indicator of insulin sensitivity, eGDR is significantly associated with both MASLD and dyslipidemia." (PMID 40672413, 2025). "One study included insulin-sensitive and insulin-resistant participants, partially representing individuals with metabolic syndrome." (PMID 40362742, 2025). "It reduces hepatic gluconeogenesis, improves insulin sensitivity, and has been shown to enhance liver function and mitigate metabolic syndrome symptoms in women with PCOS." (PMID 40729034, 2025). "Concurrently, dyslipidemia exacerbates lipotoxicity, promoting ectopic lipid deposition in the liver and skeletal muscle, which impairs insulin signaling and β-cell function." (PMID 40765936, 2025). "Adiponectin, an adipocyte-derived hormone exhibiting insulin-sensitizing and anti-inflammatory effects, plays an important role in the pathogenesis of the metabolic syndrome." (PMID 40179096, 2025).
metabolic syndrome (continued). "For instance, small mechanistic trials show that transferring stool from lean donors can transiently improve peripheral insulin sensitivity in adults with metabolic syndrome." (PMID 40575958, 2025). "By improving insulin sensitivity, promoting weight loss, and restoring glucose metabolism, GLP-1 RAs engage biological pathways relevant to both mood dysregulation and metabolic syndrome." (PMID 41010364, 2025). "Research indicates that the Mediterranean diet lowers the incidence of metabolic syndrome, improves insulin sensitivity, reduces systemic inflammation, and significantly decreases cardiovascular risk." (PMID 39861488, 2025). "The activation of CB1 receptors located in hepatocytes leads to increased lipogenesis and fatty acid synthesis, dyslipidemia, gluconeogenesis, and hepatic insulin resistance." (PMID 41096816, 2025). "Some confirmation of the effect of the gut microbiota on blood glucose levels is that transplanting the gut microbiota into patients diagnosed with metabolic syndrome resulted in increased tissue sensitivity to insulin." (PMID 40864784, 2025). "High-fat-diet treatment is standardly used to induce symptoms of metabolic syndrome in animal models, including obesity, a fatty liver phenotype, and impaired glucose homeostasis, insulin, and lipid metabolism." (PMID 40426854, 2025). "Currently, one of the most pressing global health issues is metabolic syndrome—a cluster of conditions that includes insulin resistance, lipid imbalances, central obesity and hypertension." (PMID 40283508, 2025). "Glycation products play a crucial role in the progression of insulin dysfunction and metabolic syndrome via NF-κB pathway induction." (PMID 40584440, 2025). "These fatty acids counteract the anti-lipolytic effects of insulin and facilitate increased lipid uptake by the liver, resulting in dyslipidemia and hepatic steatosis." (PMID 39794453, 2025). "High carbohydrate intake directly affects the blood glucose load in the human body to reduce insulin sensitivity, which, in turn, affects fat metabolism and ultimately leads to metabolic abnormalities such as dyslipidemia." (PMID 40964683, 2025). "A key role in the pathophysiology of metabolic syndrome is thought to be played by the rise in circulating free fatty acids via insulin resistance." (PMID 39817379, 2025). "A recent systematic review concluded that microalgae-derived supplements can enhance insulin sensitivity, modulate lipid metabolism, and lower systemic inflammation in individuals with metabolic syndrome and type 2 diabetes." (PMID 40565730, 2025). "SMM plays a major role in the pathogenesis of metabolic syndrome as it constitutes the largest insulin-sensitive tissue in the body." (PMID 39810108, 2025). "As a matter of fact, NAFLD is recognized as the hepatic component of metabolic syndrome, as both pathologies share insulin resistance as a common pathophysiological mechanism." (PMID 40727516, 2025). "Previous studies in metabolic syndrome models have indicated that fucoidan and other seaweed-derived compounds can enhance insulin sensitivity and lipid metabolism." (PMID 41010459, 2025). "Higher doses, administered at 500 mg/day over a 12-week period, have also produced favorable outcomes in individuals with metabolic syndrome, including improved insulin sensitivity and reductions in triglycerides, BMI, and blood pressure." (PMID 40944237, 2025). "One of the main characteristics of the metabolic syndrome is IR, which is characterized as reduced insulin sensitivity in peripheral organs." (PMID 40421215, 2025). "GOS also ameliorated the effects of metabolic syndrome in patients with weight gain, dyslipidaemia, and insulin sensitivity, suggesting that GOS has considerable therapeutic potential for glucose metabolism." (PMID 41395840, 2025). "For example, it mapped Akkermansia muciniphila mucin degradation pathways to improved insulin sensitivity in metabolic syndrome." (PMID 40933132, 2025).